CCL2 (C-C motif chemokine ligand 2)
Diseases named in the same sentence as CCL2 in open-access papers (continued):
Sharing a sentence is not in itself a finding about the gene and the disease.
tumor (continued). "Therefore, we investigated whether CCL2 secreted by tumor cells was associated with the activity of myeloid cells." (PMID 31780645, 2019). "Moreover, stiffed collagen-rich matrix was found to induce CAFs production of monocytic chemoattractants like CCL2 and M-CSF, and CAFs in tumor-associated fibrosis produce high levels of cytokines and chemokines that favor tumor-promoting Th2 and Th17 responses." (PMID 31428105, 2019). "Moreover, IL-6 and CCL2 induce tumor-associated macrophage polarization." (PMID 29867925, 2018). "Moreover, CCL2 suppression is associated with reduced tumor aggressiveness in BC." (PMID 30059519, 2018). "In this regard, high PIM levels increase the recruitment of tumor/inflammation associated macrophages, MDSCs, mast cells, and neutrophils to the target tissue, which can increase cytokines, such as IL-6, IL-1 and TNFa, and chemokines, such as CCL2 and CXCL8, locally." (PMID 27901106, 2016). "We further confirmed that co-cultured neutrophils are N2-type neutrophils via examining the chemokine CCL2 expression, as previous studies indicated that the CCL2 secreted by tumors could convert surrounding neutrophils into N2 type neutrophils, named as tumor-associated neutrophils (TAN)." (PMID 26517808, 2015). "Moreover, tumor cells recruit macrophages called tumor associated macrophages (TAMs) by secreting the colony stimulating factor (CSF-1), the chemokine ligand 2, 3, 4, 5, and 8 (CCL2, 3, 4, 5, and 8) and the vascular endothelial growth factor (VEGF)." (PMID 21437225, 2010). "To further examine the relationship between CCL2/GM-CSF and macrophage differentiation, we conducted multiplex immunohistochemical analysis to investigate the role of CCL2 and GM-CSF in tumor microenvironment in vivo." (PMID 41513619, 2026). "Tumor cells, fibroblasts, and stromal cells often secrete high levels of CCL2, which attracts CCR2 + monocytes to the TME." (PMID 41497137, 2026). "In tumor tissues established in vivo, the levels of CCL2 and GM-CSF were also significantly up-regulated in N4BP1-deficient tumors compared to controls, as examined by RT-PCR, western blotting (WB), immunohistochemistry (IHC), and immunofluorescence (IF)." (PMID 41513619, 2026). "FAs released from adipose tissue activate HIF‐1α in cancer cells, which in turn increases the secretion of CCL2, promoting tumor growth and metastasis." (PMID 41160815, 2026). "Due to the critical role of CCL2 and GM-CSF in macrophage recruitment and differentiation, we culture control and N4BP1-deficient tumor cell with activated THP-1 cells." (PMID 41513619, 2026). "We found that tumor‐derived CCL2 acitively upregulates PPARα, a key transcription factor in lipid metabolism, thereby promoting adipose lipolysis and the release of FAs." (PMID 41160815, 2026). "A consistent pattern emerged, supporting previous findings: the expression levels of HIF‐1α, CCL2, and Ki67 in tumor tissues increased progressively with higher BMI." (PMID 41160815, 2026). "This increased availability of lipids has a more pronounced effect on tumor progression, leading to a stronger tumor‐suppressive response when CCL2 is blocked." (PMID 41160815, 2026). "Our in vivo experiments demonstrated that disrupting the tumor‐adipose tissue feedback loop with nAb‐CCL2 not only inhibited tumor growth but also decreased lipolysis in tumor‐adjacent adipose tissue, thereby preserving its volume in the HFD group." (PMID 41160815, 2026). "The tumor suppression effects of CCL2 inhibitor (Pirfenidone) and CXCR3 inhibitor (AMG487) are validated in the orthotopic tumor model." (PMID 42295734, 2026). "In obese mice, this reciprocal signaling accelerated tumor progression, whereas intra‐tumoral injection of CCL2‐neutralizing antibody significantly suppressed it." (PMID 41160815, 2026). "Survival analysis showed that patients with elevated CCL2 levels in tumor tissues had significantly shorter overall survival (P < 0.001)." (PMID 42038362, 2026).
tumor (continued). "For example, tumor cells secrete CCL2 (also called MCP-1) and TGFβ to attract and activate monocytes to generate angiogenic factors for tumor cell growth." (PMID 41513619, 2026). "The resulting fatty acid influx amplifies HIF‐1α/CCL2 signaling, establishing a positive feedback loop that fuels tumor growth." (PMID 41160815, 2026). "The increased lipid supply to tumor reactivates the FA/HIF‐1α/CCL2 axis in cancer cells, further accelerating tumor growth and CCL2 secretion." (PMID 41160815, 2026). "In contrast, nAb‐CCL2 treatment inhibited lipolysis, preserving adipose tissue volume and suppressing tumor progression by reducing FA supply." (PMID 41160815, 2026). "The results show that the tumor promotes lipolysis in surrounding adipose tissue by secreting CCL2, which reduces fat pad volume." (PMID 41160815, 2026). "The lack of significant difference between N.A. and T.A. tissues following CCL2 neutralizing antibody treatment suggests that blocking CCL2 inhibits tumor‐induced lipolysis, supporting earlier in vitro findings." (PMID 41160815, 2026). "Tumor-associated macrophages (TAMs) are macrophages that are recruited and infiltrate tumor tissue by tumor-derived chemotactic factors such as macrophage colony-stimulating factor (M-CSF), CCL2, and CCL551." (PMID 39781471, 2025). "MDSCs are recruited to hypoxic tumor areas via CCL2 and CXCL12, express PD-L1 and suppress antigen presenting cells function affecting DC maturation and impairing T cell priming." (PMID 40963621, 2025). "Meanwhile, PCR results indicated high expression of TNF and CCL2 in tumor samples, confirming this effect at the genetic level." (PMID 39865310, 2025). "Limitations of the mechanism of action: Neutralization strategies can only temporarily block extracellular CCL2 but cannot silence CCL2 at its source, thus failing to restore the homeostasis of CCL2 in the tumor microenvironment." (PMID 41341593, 2025). "Recruitment of MDSCs to the TME is primarily orchestrated by chemokines such as CCL2, secreted by tumor cells, stromal cells, and immune components within the TME." (PMID 40563359, 2025). "When CCL2 binds to the C-C chemokine receptor type 2 (CCR2) on the tumor cells, it enhances mobility and directs their infiltration into brain tissue." (PMID 39858080, 2025). "These cells are recruited and activated by chemokines such as CCL2, which plays a pivotal role in shaping the immune landscape of the tumor." (PMID 40940890, 2025). "Monoclonal antibodies targeting CCL2 have been shown to effectively reduce macrophage accumulation in preclinical tumor models and enhance anti-tumor efficacy when combined with conventional chemotherapy." (PMID 40563367, 2025). "Chemokines released by tumor cells play crucial roles in recruiting monocyte-macrophage lineages during tumor progression, with CCL2 serving a particularly central function." (PMID 41417432, 2025). "Cytokines including, IL-6, and IL-1β engage in positive feedback interactions with CCL2 in the TME—a phenomenon with important implications for tumor therapy." (PMID 41341593, 2025). "CAAs play an essential role in promoting tumor progression by secreting multiple adipokines, such as CCL2, CCL5, leptin, and adiponectin." (PMID 40248695, 2025). "Migration of immune cells to tumor sites, meanwhile CCL2/8-CCR2 axis had the function of chemotactic mononuclear/macrophage cells and CD8+ T cells." (PMID 40098106, 2025). "dl922-947-induced reduction of IL-8 and CCL2 production correlates with impaired tumor angiogenesis and decreased macrophage density." (PMID 40698086, 2025). "Chemotherapy, for instance, was reported to enhance CCL2-driven (classical) monocyte recruitment and differentiation into tumor-promoting M2 macrophages, thereby reducing the adaptive anti-tumor immunity." (PMID 41440002, 2025).
tumor (continued). "Meanwhile, CCL2 chemokine production attracts monocytes and neutrophils to collaborate in tumor-supportive processes, including vascular remodeling, metastasis, and immune suppression." (PMID 40281554, 2025). "TAMs, predominantly derived from monocytes recruited via chemokines like CCL2 and M-CSF, are profoundly shaped by this milieu and adopt functional phenotypes that facilitate immune evasion, angiogenesis, metastasis, and tumor cell proliferation." (PMID 41459539, 2025). "Chemokine ligand 2 (CCL2) recruits monocytes expressing chemokine receptor 2 (CCR2) from the peripheral blood to the tumor site, where they further mature into TAMs." (PMID 40191203, 2025). "In clinical diagnostics, specific chemokines (e.g., CXCL8 and CCL2) serve as valuable biomarkers, with their expression levels demonstrating significant correlations with tumor stage and prognosis." (PMID 41445742, 2025). "CAFs recruit monocytes to tumor sites by releasing SDF-1 (via the SDF-1/CXCR4 axis) and CCL2 (monocyte chemoattractant protein-1, MCP-1), inducing their differentiation into M2 macrophages that further promote tumor invasion and metastasis." (PMID 41514658, 2025). "Tumour-associated macrophages (TAMs) are attracted to the TME through cytokines and chemokines, including VEGF, CSF-1, TGF-β, CCL2, CCL7, and CCL8." (PMID 40507298, 2025). "CCL-2 participates in the initiation of inflammatory responses by recruiting several immune cells to the allergic inflammation site or to the tumor microenvironment." (PMID 40362499, 2025). "FMD intervention disrupts this pathogenic cycle through dual mechanisms - directly impairing tumor cell CCL2 production and indirectly modulating TAMs effector functions - thereby resensitizing malignancies to EGFR-targeted therapy." (PMID 40808689, 2025). "In the tumor microenvironment, chemokines such as CCL2, CCL3, CCL4, and CCL5 attract monocytes that differentiate into TAMs." (PMID 39941858, 2025). "Classical monocytes, drawn by tumor-derived chemokines like CCL2, differentiate into TAMs and support immunosuppression, whereas nonclassical monocytes possess antimetastatic properties." (PMID 40940890, 2025). "CCL2 was responsible for recruiting bone marrow-derived immunosuppressive cells and promoting the construction of a tumor immunosuppressive environment." (PMID 40535567, 2025). "In the TME, elevated CCL2-mediated chemotaxis recruits CCR2+ circulating monocytes to the tumor site, thereby contributing to the establishment of an immunosuppressive TME." (PMID 40700478, 2025). "Collectively, our data suggest that the AKT/IKK/NF‐κB pathway in PDPN(+) CAFs regulates CCL2 secretion, which subsequently stimulates angiogenesis and tumor growth." (PMID 39764562, 2025). "There is evidence that CAFs recruit both types of MDSCs to tumor sites in lung squamous cell carcinoma (LSCC) by releasing CCL2, which is a crucial activator for the STAT3 signaling pathway." (PMID 40805183, 2025). "Among these, CCL2 is particularly crucial for directing monocytes from peripheral blood into the tumor, where engagement with CCR2 initiates their differentiation into TAMs." (PMID 40630800, 2025). "Specifically, tumor- and stromal-derived Ccl2 is known to promote monocyte recruitment, which is required for lung metastasis." (PMID 39566333, 2025). "CCL2 is overexpressed in tumor cells while its receptor CCR2 is exclusively expressed in immunosuppressive cells, conferring CCL2-CCR2 as an oncogenic axis." (PMID 40148310, 2025). "Immune modulatory molecules, such as CCL2 and CCL5, which recruit tumor-associated macrophages, and adhesion molecules ICAM1 and VCAM1, which facilitate immune cell trafficking, were also included." (PMID 40652770, 2025). "It is worth noting that CCL2 can inhibit the normalization of induced blood vessels, while anti-CCL2 therapy can induce blood vessel normalization and improve tumor perfusion, thereby enhancing tumor-targeted drug delivery and anti-cancer nanotherapy." (PMID 41445742, 2025).
tumor (continued). "In glioblastoma animal models, inhibitors targeting the CCR2/CCL2 axis have been shown to significantly reduce M2-type TAM infiltration at tumor sites, leading to improved survival outcomes." (PMID 41019045, 2025). "Tumor microenvironment (TME) soluble mediator (Ccl2, Ccl3, Ccl4, Ccl5) and tumor cell marker (NeuN, Gpr17) RNA expression was quantitated by qRT-PCR." (PMID 41497446, 2025). "In vivo experiments demonstrated that while primary tumor growth was unaffected, administration of CCL2-neutralizing antibody led to a significant suppression of lung metastasis and infiltration of M2-like TAMs in the lung tissue." (PMID 40343498, 2025). "For example, CCL2 promotes tumor progression by stimulating AKT phosphorylation, thereby enhancing invasion and metastasis." (PMID 40430079, 2025). "These protein kinases we identified being activated in OS EV–primed LFs are also known drivers of the secretion of key tumor-promoting cytokines and chemokines such as IL-6, IL-8, and CCL2 across a range of cell types, including fibroblasts." (PMID 40099972, 2025). "For instance, secreted circulating factors such as IL6, IL-1Ra, and CCL2 have been found to initially increase in patients after PD-1 pathway inhibition and correlate with tumor stabilization/shrinkage, as measured by objective response rates (ORR)." (PMID 39663510, 2025). "Their recruitment, differentiation, and function are tightly regulated by tumor-derived chemotactic factors such as CCL2 and CSF1." (PMID 41002423, 2025). "Tumor cell-secreted chemokines, like CCL2, recruit bone marrow-derived monocytes and promote their differentiation in the tumor site." (PMID 39858465, 2025). "Cancer-associated adipocytes secrete the chemokines CCL2/5 and IL-6/TNF-α, which promote tumour proliferation and immune escape by binding to CXCR2 and IL-6R/TNF-R on the surface of tumour cells." (PMID 40414892, 2025). "Accordingly, these cells produce high levels of pro-inflammatory cytokines, such as TNF, IL-1β, IL-6, IL-12, IL-23, and CCL2, to promote immune responses against bacteria, intracellular pathogens, and tumor cells." (PMID 40109347, 2025). "The cytokine analysis of LLC and MC38 tumor cell lines revealed substantial expression of CCL2 and CXCL10, as observed previously." (PMID 39566333, 2025). "For instance, CCL2 (MCP-1) and CXCL12 (SDF-1α) are well-documented drivers of monocyte chemotaxis, promoting their differentiation into M2-like tumor-associated macrophages (TAMs) that foster angiogenesis and immunosuppression." (PMID 41293263, 2025). "Gene knockout experiments further demonstrated that CCL2 inhibition reduces BMDM recruitment, delays tumor progression, and prolongs survival in murine models, suggesting that the CCL2/CCR2 axis is a potential therapeutic target for GBM immunotherapy." (PMID 41002423, 2025). "Lastly, we show that Ccl2-knock-down tumor cells in Ccr1-/- mice leads to virtual impairment of lung metastasis." (PMID 39566333, 2025). "Concurrently, oxLDL-derived ROS upregulate chemokines CXCL1/CCL2, recruiting MDSCs from the bone marrow to the tumor site and forming a self-reinforcing “ROS-chemokine-MDSC infiltration” feedback loop." (PMID 40563359, 2025). "CCL2, the prototypical member of the CC chemokine family, has emerged as a critical mediator of tumor progression and therapeutic resistance." (PMID 41276817, 2025). "The overexpression of HMGA2 in CRC cells promoted macrophage recruitment and M2 polarization by upregulating STAT3-mediated CCL2 secretion, thereby promoting tumor immune suppression in CRC." (PMID 40703517, 2025). "We identified specific subtypes of stromal and immune cells critical to forming a pro-tumor microenvironment in metastatic lesions, including CCL2+ macrophages, exhausted cytotoxic T cells, and FOXP3+ regulatory T cells." (PMID 40858590, 2025).
tumor (continued). "The current findings, derived from in vitro experiments using THP-1-differentiated M2 macrophages, provide valuable insights into the regulatory mechanisms involved in CCL2 expression under tumor-mimicking ionic conditions." (PMID 40806751, 2025). "have demonstrated that co-culturing breast tumor cells with adipocytes results in increased expression of CCL2, leading to enhanced recruitment of monocytes/macrophages to the tumor site." (PMID 41200178, 2025). "TENs inhibit metastatic seeding in the lungs and acquire cytotoxic phenotypes in tumor cells, which is related to the secretion of chemokine (C-C motif) ligand 2 (CCL2) by the tumor cells." (PMID 40282474, 2025). "There is also evidence that CCL-2 gene expression can be upregulated in tumor cells by inflammatory mediators, such as TNF or TGF-β." (PMID 40362499, 2025). "The IL-6 secretion upregulated by tumor exosomal cSERPINE2-educated TAMs enhanced CCL2 expression, and thereby, TAMS infiltration into TME was enhanced." (PMID 40443670, 2025). "By binding to its receptor CCR2, CCL2 mainly promotes the recruitment of monocytes and pro-macrophages to the tumor microenvironment." (PMID 40109347, 2025). "After undergoing EMT, tumor cells typically release increased levels of chemokines (such as CCL2), further promoting the recruitment and polarization of TAMs." (PMID 40304000, 2025). "Tumor cells release CCL2, a potent chemoattractant for CCR2-expressing myeloid cells, including tumor-associated macrophages (TAMs) and myeloid-derived suppressor cells (MDSCs)." (PMID 40867316, 2025). "This study provides a theoretical basis for understanding the tumor regulatory network of CCL2 and the development of precise targeted therapy." (PMID 41341593, 2025). "Tumor-derived lactate drives transcriptional reprogramming (CCL2, ARG1, IL10, S100A9) in TAMs via the ENSA-K63la/STAT3-pY705 axis, promoting an immunosuppressive environment and immunotherapy resistance." (PMID 39883522, 2025). "miRNA mediates FOXO3a/VEGF/CCL2 signaling to promote tumor growth, angiogenesis, TAMs accumulation and lung metastasis." (PMID 41341593, 2025). "Some studies have associated this axis with the expression of nonmalignant cells in the tumor microenvironment (TME), while others have described that the inhibition of CCL2 reduced tumor metastasis by affecting macrophage infiltration." (PMID 39305371, 2025). "Both tumor cells and TAMs amplify CCL2 production, thereby creating a positive feedback loop that further promotes TAM accumulation and proliferation." (PMID 41058699, 2025). "Muc16-directed CAR-T cells engineered to express CCR2, the cognate receptor to CCL2, demonstrate better in vitro and in vivo tumor-directed trafficking and improve survival in tumor-bearing mice." (PMID 41424784, 2025). "In agreement, immunofluorescent staining of GC patient tumor samples revealed that CCL2 was abundantly expressed in PDPN(+) CAFs." (PMID 39764562, 2025). "Previous studies have implicated signaling pathways and cytokines such as CCL8, CCL2/CCR2, CSF-1/CSF-1R, STAT3, STAT6, MMPs, AMPK, TLR3, and SIRPα in the regulation of TAMs and tumor progression." (PMID 39781471, 2025). "MCP-1 (also known as CCL2, chemokine (C-C motif) ligand 2) overexpression has been linked to tumor growth, angiogenesis, and poor prognosis across multiple cancer types, and elevated serum MCP-1 correlates with tumor stages in various malignancies." (PMID 40426911, 2025). "Exosomal CCL2 secreted by tumor cells primarily accumulates in the primary tumor, with a small amount being taken up by CCR2+ myeloid‐derived suppressor cells and CCR2+ NK cells, promoting tumor metastasis." (PMID 39712454, 2025). "In this context, senescent tumor cells can be a robust source of CCL2 and possibly participate in neuropathic pain." (PMID 41306965, 2025).